LGALS7 (galectin 7)
Diseases named in the same sentence as LGALS7 in open-access papers (continued):
Sharing a sentence is not in itself a finding about the gene and the disease.
ovarian cancer (11 papers, 2014 to 2026). A primary or metastatic malignant neoplasm involving the ovary. "Pro-invasive and pro-metastatic functions of galectin-7 were associated with increased expression of MMP2 and MMP9 in oral squamous cells and ovarian carcinoma." (PMID 36873388, 2023). "Galectin-7 is secreted by ovarian cancer cells and is involved in the regulation of tumor invasiveness." (PMID 36873388, 2023). "Lower galectin-7 expression was confirmed as an independent prognostic factor for overall survival in ovarian cancer." (PMID 34827718, 2021). "It was found that galectin-7 increased the invasive behavior of ovarian cancer cells by inducing MMP-9 and increasing cell motility." (PMID 34827718, 2021). "Galectin-7 is expressed in abnormally high levels most notably in breast and ovarian cancer cells." (PMID 36817445, 2023). "The observation that galectin-7 may have immunosuppressive properties was made by Labrie and co-workers while investigating the expression of galectin-7 in epithelial ovarian cancer (EOC)." (PMID 34827718, 2021). "In another example, where the expression of galectin-7 in epithelial ovarian cancer (EOC) is evaluated, it was observed that extracellular galectin-7 is released outside the cells." (PMID 34827718, 2021). "In contrast, in benign and malignant ovarian tumours, an increase in galectin-7 expression has been shown, while no galectin-7 expression has been reported in healthy ovarian tissue." (PMID 37238197, 2023). "Although it was proposed that galectin-7 serves as a negative prognostic factor in ovarian cancer by two independent groups, Schulz and colleagues studied the prognostic value of galectin-7 (among other galectins) in patients with epithelial ovarian cancer." (PMID 34827718, 2021). "Galectin-7 has been proposed to serve as negative prognostic factor in ovarian cancer by two independent groups." (PMID 28594391, 2017).
lymphoma (10 papers, 2007 to 2024). A malignant (clonal) proliferation of B- lymphocytes or T- lymphocytes which involves the lymph nodes, bone marrow and/or extranodal sites. "It was reported that high expression of galectin-7 in 164T2 lymphoma cells was associated with an increased recurrence rate and poor prognosis." (PMID 35677161, 2022). "Conversely, inhibition of galectin-7 in aggressive lymphoma variants decreased their invasive behavior in vivo." (PMID 34198494, 2021). "Highly metastatic variants of the lymphoma cell line showed strong upregulation of galectin-7 in the spleen, the thymus and kidneys, due to the methylation of the galectin-7 gene (LGALS7)." (PMID 34827718, 2021). "Overall, the positive regulatory effect of galectin-7 on lymphoma provides us with a new therapeutic direction." (PMID 35677161, 2022). "DNA methylation induced galectin-7 and is usually related to the evolution of lymphoma cells into highly aggressive tumor cells." (PMID 35677161, 2022). "Galectin-7 cDNA transfection significantly suppresses the dissemination and invasion of lymphoma cells and increases the survival of mice." (PMID 35677161, 2022). "Transfection of an expression vector containing the galectin-7 gene into low-metastatic lymphoma cells increased their metastatic behavior." (PMID 34198494, 2021). "Galectin-7 does not only have a role in carcinomas, but also in lymphomas and melanomas by contributing either to neoplastic transformation and tumor progression through the regulation of cell growth, cell cycle, angiogenesis, apoptosis and cell migration." (PMID 34827718, 2021). "It was first reported in an experimental lymphoma mouse model, in which the expression of galectin-7 by lymphoma cells was shown to increase the aggressive behavior of lymphoma cells by inducing MMP-9." (PMID 34198494, 2021). "In continuation, the same group found evidence that galectin-7 is expressed in human lymphoid malignancies and proposed that it is a critical tumor-modulating gene that controls the dissemination of lymphoma cells via MMP-9." (PMID 34827718, 2021). "It was shown that galectin-7 is constitutively expressed in aggressive (metastatic) lymphoma cells at both mRNA and protein levels." (PMID 34827718, 2021). "In lymphomas, ectopic expression of galectin-7 was shown to correlate with the metastatic potential of transplanted lymphomas cell lines." (PMID 29257082, 2017). "Promoter hypomethylation is at the basis of the up-regulation of galectin-7 during lymphoma progression, while promoter hypermethylation is responsible for galectin-7 downregulation in gastric cancer, a tumor in which it has a tumor suppressive function." (PMID 28481247, 2017). "Indeed, in lymphoma cells or in HeLa cells, exogenously added galectin-7 was able to enhance MMP-9 expression, suggesting a potential role for galectin-7 in the regulation of cell–ECM adhesion during cancer dissemination." (PMID 29257082, 2017). "Furthermore, the ability to inhibit galectin-7 to decrease tumor invasion and metastasis may become a new therapeutic strategy for lymphoma." (PMID 35677161, 2022). "Furthermore, murine or human recombinant galectin-7 induces the expression of MMP-9 in both mouse and human lymphoma cells." (PMID 34827718, 2021). "Using our lymphoma model, we further provided evidence that such upregulation of galectin-7 in lymphoma cells is not an epiphenomenon." (PMID 34198494, 2021).
cervical carcinoma (7 papers, 2016 to 2024). A carcinoma arising from either the exocervical squamous epithelium or the endocervical glandular epithelium. "As galectin-7 is negatively regulated in cervical cancer, Higareda-Almaraz and co-workers demonstrated the link between the pro-apoptotic response triggered by cancer and the anti-tumoral activity of the immune system." (PMID 34827718, 2021). "Galectin-7 re-expression affects the regulation of molecular networks in cervical cancer that are involved in some of the cancer hallmarks, such as metabolism, growth control, invasion and evasion of apoptosis." (PMID 34827718, 2021). "In this review, we mainly focus on the role of galectins, especially galectin-1, galectin-3, galectin-7, and galectin-9 in cervical cancer, and provide theoretical basis for potential targeted treatment of cervical cancer." (PMID 29854732, 2018). "As an illustration, de novo expression of galectin-7 in the cervical cancer HeLa cells and in the colorectal adenocarcinoma DLD-1 cell line makes these cells more sensitive to the induction of apoptosis by UVB irradiation or diverse chemical apoptotic stimuli." (PMID 29257082, 2017). "Galectin-7 (Gal-7) is negatively regulated in cervical cancer, and appears to be a link between the apoptotic response triggered by cancer and the anti-tumoral activity of the immune system." (PMID 27558259, 2016). "Different members of the galectin family, such as galectin-1 (Gal-1) and galectin-7 (Gal-7), have been found to influence the pathogenesis of cervical cancer (CaCx)." (PMID 27558259, 2016). "Targeting galectin-7 may be considered a chemoradiotherapy therapy for cervical cancer." (PMID 34485140, 2021). "For example, galectin-7 produces a CCRT response and acts as a significant predictor for cervical cancer patients treated with definitive radiation therapy." (PMID 37519786, 2023). "Similarly, overexpression of galectin-7 in ST88-14 cells, a sarcoma-derived cell line, in the cervical carcinoma siHa cells or in the prostate cancer cells DU-145 results in an increased susceptibility of the cells to apoptotic stimuli." (PMID 29257082, 2017).
melanoma (7 papers, 2013 to 2025). A malignant, usually aggressive tumor composed of atypical, neoplastic melanocytes. "Although galectin-7 rendered B16F1 melanoma cells resistant to apoptosis but also inhibited cancer cell motility through increased expression of early growth response protein 1 (EGR-1)." (PMID 36873388, 2023). "Contrastingly, one of the major skin cancers apart from melanomas, basal cell carcinoma, appeared to be devoid of galectin-7 expression while galectin-7 is expressed in normal tissues." (PMID 29257082, 2017). "We also found that overexpression of galectin-7 is insufficient to modulate the growth of primary tumors or the dissemination of B16 melanoma cells to the lung." (PMID 23658821, 2013). "In the present work, we have shown that 1) galectin-7 is rarely expressed in biopsies of malignant melanoma, 2) galectin-7 reduces the motility of B16F1 cells, and 3) galectin-7 increases the resistance of B16F1 cells to apoptosis and the expression of EGR-1." (PMID 23658821, 2013). "In the present work, we have investigated the expression pattern of galectin-7 in melanoma and used a well-characterized melanoma model to study its functional relevance." (PMID 23658821, 2013). "Our in vivo results using stable transfectants overexpressing galectin-7 suggest, however, that if indeed galectin-7 can be found in rare cases of melanoma, it probably plays a very limited role in tumor growth and apoptosis." (PMID 23658821, 2013). "Because melanoma represents one of the most dangerous forms of skin cancer, we investigated the role of galectin-7 in melanoma." (PMID 23658821, 2013). "Using the experimental melanoma B16F1 cell line, we found that melanoma cells can express galectin-7 at the primary tumor site and in lung metastasis." (PMID 23658821, 2013). "Our data showing that galectin-7 reduces the motility of melanoma cells are novel and worth investigating further in the context of the ability of Bcl-2 to bind galectin-7." (PMID 23658821, 2013). "To study the effect of galectin-7 on melanoma metastasis, we used genetically engineered B16F1 cells overexpressing luciferase." (PMID 23658821, 2013). "In biopsies obtained from patients with malignant melanomas, galectin-7 expression was relatively rare (9/45)." (PMID 23658821, 2013). "Low expression levels of galectin-7 were also observed in both human and mouse malignant melanoma cell lines." (PMID 23658821, 2013). "The importance of galectin-7 in melanoma is thus very distinct from what has been observed in other types of epithelial cancer." (PMID 23658821, 2013). "Future IHC analysis on normal melanocytes and in a larger number of biopsies of nevus and melanoma are needed to determine the utility of galectin-7 as a predictive biomarker in melanom." (PMID 23658821, 2013). "This upregulation of galectin-7 in B16 melanoma cells in vivo was also observed in lung biopsies of KOG7 mice injected i.v. with B16 cells." (PMID 23658821, 2013). "In melanoma cells, the expression of galectin-7 was shown on primary tumors and lung metastases." (PMID 39465762, 2024). "Studies were also conducted to investigate the role of galectin-7 in melanoma." (PMID 29257082, 2017). "However, even if galectin-7 increased the resistance of melanoma cells to apoptosis, studies on the melanoma cell line B16F1 showed that galectin-7 ectopic expression did not impact tumour growth and metastasis occurrence when cells are injected into mice." (PMID 29257082, 2017). "Indeed, tissue analysis on human melanomas and nevi first showed an expression of galectin-7 but in situ labelling of nevi biopsies suggested that they were mostly the keratinocytes subpopulation of the biopsies that expressed galectin-7." (PMID 29257082, 2017). "However, in the breast MCF-7 cancer cells or in the B16F1 melanoma cell line, ectopic expression of galectin-7 decreases the cell sensitivity to apoptotic stimuli, indicating that galectin-7 can also, contrastingly, have an anti-apoptotic effect." (PMID 29257082, 2017).
melanoma (continued). "In the present work, we investigated the expression and function of galectin-7 in melanoma." (PMID 23658821, 2013). "Nevertheless, our results showing that B16 cells do express galectin-7 when transplanted in vivo leaves open the possibility that in rare cases, galectin-7 could be expressed in malignant melanoma cells." (PMID 23658821, 2013). "Moreover, we found that overexpression of galectin-7 increased the resistance of melanoma cells to apoptosis while inducing de novo egr-1 expression." (PMID 23658821, 2013). "Interestingly, however, we found that galectin-7 can be upregulated in B16 melanoma cells that had been injected subcutaneously into normal C57BL/6 syngeneic mice." (PMID 23658821, 2013). "A number of indications have suggested that galectin-7 may potentially be important in melanoma proliferation, invasion, and metastasis." (PMID 23658821, 2013). "We next investigated whether galectin-7 could modulate the tumor progression of B16 melanoma cells." (PMID 23658821, 2013). "An analysis of datasets obtained from whole-genome profiling of human melanoma tissues revealed that galectin-7 mRNA was detected in more than 90% of biopsies of patients with nevi while its expression was more rarely found in biopsies collected from patients with malignant melanoma." (PMID 23658821, 2013). "Galectin-7 expression was strongly enhanced by insulin growth factor 1 (IGF-1) and cyclooxygenase-2 (COX-2) in melanoma." (PMID 36873388, 2023). "In contrast, melanoma cells of the dermal compartment had significantly lower expression of TACSTD2 and LGALS7, amongst others." (PMID 37602975, 2023). "Among those, even fewer studies explored the ectopic expression of galectin-7 in tumours from non-epithelial origins such as lymphoid or melanomas tumours." (PMID 29257082, 2017). "In addition, it has been found that when the melanoma cells B16F1 are injected subcutaneously into mice, galectin-7 can be expressed by the resulting primary tumour as well as in lung metastasis." (PMID 29257082, 2017). "However, ectopic expression of galectin-7 in the B16F1 melanoma cell line did not affect cell growth indicating that cell context might be important for galectin-7 to modulate cell proliferation." (PMID 29257082, 2017).
psoriasis (7 papers, 2021 to 2025). An autoimmune condition characterized by red, well-delineated plaques with silvery scales that are usually on the extensor surfaces and scalp. "Previous studies have shown that LGALS7 expression is reduced in lesional skin from patients with psoriasis and that this reduction is associated with keratinocyte hyperplasia via increased cytokine (IL-6 and IL-8) expression and ERK signaling." (PMID 37805522, 2023). "The upregulation of NEAT1 is reported to result in the targeted mediation of downstream miR-3194-5p to increase Galectin-7 expression, which subsequently inhibits the activity of psoriasis HaCat cells and exhibits therapeutic effects." (PMID 40725409, 2025). "Paeoniflorin controls the proliferation and migration of psoriasis HaCat cells through the NEAT1/miR-3194-5p/Galectin-7 axis." (PMID 40110044, 2025). "In skin inflammation such as psoriasis, Gal-3 and galectin-7 (Gal-7) suppress neutrophil recruitment by downregulating pro-inflammatory chemokines and signaling pathways." (PMID 40806347, 2025). "LncRNA-NEAT1 and Galectin-7 are lowly expressed in psoriasis patients, while miR-3194-5p is highly expressed." (PMID 40110044, 2025). "Galectin-7 was found to play a role in the pathogenesis of psoriasis, an inflammatory process affecting stratified squamous cells of the skin by elevating levels of IL-6 and IL-8." (PMID 34638303, 2021). "Galectin-7 expression is low in psoriasis and enhances keratinocyte sensitivity to IL-17A.." (PMID 37762693, 2023). "Paeoniflorin inhibits the proliferation and migration of psoriasis HaCat cells by upregulating the expression of lncRNA-NEAT1 and Galectin-7." (PMID 40110044, 2025).
gastric cancer (6 papers, 2013 to 2025). A primary or metastatic malignant neoplasm involving the stomach. "We also determined the effect of loss of function of galectin-7 in KATO III gastric cancer cells, which have high expression levels of galectin-7." (PMID 23985992, 2013). "They revealed significantly lower expression levels of galectin-7 in malignant tissues of gastric cancer patients, compared with matched normal tissues." (PMID 34827718, 2021). "Methylation of the LGALS7 gene, leading to the silencing of galectin-7 during gastric cancer tumorigenesis, was also suggested by Kim and colleagues." (PMID 34827718, 2021). "The present study further demonstrated that knockdown of Tid1 contributes to cell migration and invasion through the galectin-7-MMP-9 axis in gastric cancer cells." (PMID 33233689, 2020). "Taken together, our results indicate that galectin-7 expression is regulated by DNA methylation in various cancer cell lines from different organ origins, including gastric cancer cell lines." (PMID 23985992, 2013). "Strong expression was detected in normal tissues from patients with intestinal and diffuse types of gastric cancer and most of the galectin-7 was localized in the cytosol." (PMID 23985992, 2013). "Our data suggest that the expression of galectin-7 in gastric cancer is regulated by DNA hypermethylation." (PMID 23985992, 2013). "To determine the expression levels of galectin-7 in gastric cancer patients, we prepared a tissue microarray (TMA) of 44 patients and performed immunohistochemical analysis." (PMID 23985992, 2013). "We selected AGS gastric cancer cells with low expression of Galectin-7 and transiently transfected them with the expression vector pQE-9-galectin-7 for 48 h." (PMID 23985992, 2013). "Taken together, our data indicate that galectin-7 has a tumor suppressive function, and that the gene is epigenetically modified by DNA methylation and significantly down-regulated in gastric cancer." (PMID 23985992, 2013). "Taken together, these findings suggest that galectin-7 has a suppressive role in gastric cancer and that its expression is regulated by epigenetic mechanisms such as DNA methylation." (PMID 23985992, 2013). "First, we examined the expression levels of galectin-7 mRNA and protein in nine gastric cancer cell lines." (PMID 23985992, 2013). "More than 70% hypermethylation was observed in 7 of 9 gastric cancer cell lines tested and 5-aza-cytidine treatment lowered galectin-7 expression by reducing methylation in 24 cancer cell lines from five different organ origins." (PMID 23985992, 2013). "The observed increase in expression of galectin-7 in gastric cancer cell lines following 5-aza-dC treatment strongly supports the involvement of epigenetic regulation in cancer cell-specific expression." (PMID 23985992, 2013). "In conclusion, given the importance of early detection for improving gastric cancer survival outcomes, the results of this study indicate that DNA methylation of galectin-7 is a promising candidate biomarker for application in gastric cancer." (PMID 23985992, 2013). "We show that the expression of galectin-7 was lower in malignant tissues than normal gastric tissues, and over-expression of galectin-7 suppressed the proliferation, migration, and invasion of gastric cancer cells." (PMID 23985992, 2013). "Next, we quantitatively analyzed the methylation status of galectin-7 in nine gastric cancer cell lines." (PMID 23985992, 2013).